SRSF6 (serine and arginine rich splicing factor 6)
Description:
Plays a role in constitutive splicing and modulates the selection of alternative splice sites. Plays a role in the alternative splicing of MAPT/Tau exon 10. Binds to alternative exons of TNC pre-mRNA and promotes the expression of alternatively spliced TNC. Plays a role in wound healing and in the regulation of keratinocyte differentiation and proliferation via its role in alternative splicing.
Synonyms: SFRS6; SRP55; B52; HEL-S-91
Tractability: PROTAC: UniProt records ubiquitination sites on it; ubiquitination databases record sites on it; its protein half-life has been measured.
Gene: Protein-coding gene on chromosome 20 (43,457,893 to 43,466,046, forward strand). Ensembl gene ENSG00000124193.
Subcellular location: Nucleus; Nucleus speckle
Subcellular location (Human Protein Atlas): Nuclear speckles
Pathways (Reactome):
Metabolism of RNA: Processing of Capped Intron-Containing Pre-mRNA; Transport of Mature mRNA derived from an Intron-Containing Transcript; mRNA 3'-end processing; mRNA Polyadenylation; mRNA Splicing - Major Pathway; mRNA Splicing - Minor Pathway
Disease: Dengue Virus-Host Interactions
Gene Ontology:
Molecular function: pre-mRNA binding; protein binding; RNA binding; nucleic acid binding
Biological process: alternative mRNA splicing, via spliceosome; mRNA splice site recognition; negative regulation of keratinocyte differentiation; negative regulation of mRNA splicing, via spliceosome; positive regulation of epithelial cell proliferation involved in lung morphogenesis; regulation of alternative mRNA splicing, via spliceosome; regulation of keratinocyte proliferation; regulation of wound healing; mRNA processing; negative regulation of gene expression; negative regulation of type B pancreatic cell apoptotic process; response to insulin; RNA splicing, via transesterification reactions
Cellular component: nuclear speck; nucleus; nucleoplasm
Genetic constraint (gnomAD): Loss-of-function variants: 17 observed, 39.89 expected, observed/expected ratio (o/e) 0.43, 90% interval 0.29 to 0.64. The synonymous counts are far from expectation, so gnomAD's model fits this gene poorly and the ratio says little. Missense variants: 379 observed, 451.32 expected, observed/expected ratio (o/e) 0.84, 90% interval 0.77 to 0.91. Synonymous variants: 204 observed, 163.29 expected, observed/expected ratio (o/e) 1.25, 90% interval 1.11 to 1.4.
Homologues: Orthologues: chimpanzee SRSF6 (99% identical), macaque SRSF6 (99% identical), dog SRSF6 (98% identical), pig SRSF6 (97% identical), mouse Srsf6 (97% identical), rat Srsf6 (97% identical), guinea pig SRSF6 (87% identical), tropical clawed frog srsf6 (75% identical), zebrafish srsf6b (73% identical), zebrafish srsf6a (68% identical), rabbit SRSF6 (61% identical). Paralogues in human: SRSF4 (70% identical), SRSF5 (48% identical), SRSF1 (34% identical), SRSF7 (29% identical), SRSF9 (26% identical), RSRC2 (23% identical), SRSF3 (22% identical), RSRP1 (20% identical).
Diseases named in the same sentence as SRSF6 in open-access papers:
SRSF6 is named in the same sentence as 67 diseases in open-access papers, as found by Europe PMC text mining. Sharing a sentence is not in itself a finding about the gene and the disease. The quoted sentences say what the papers report.
colorectal cancer (25 papers, 2014 to 2025). A primary or metastatic malignant neoplasm that affects the colon or rectum. "The lncRNA LINC01133 promotes nuclear sequestration of SRSF6, preventing SRSF6-associated epithelial-mesenchymal transition and metastasis in colorectal cancer mouse models." (PMID 34196950, 2022). "SRSF6 is often upregulated in colorectal cancer and associated with worse prognosis." (PMID 35984577, 2022). "Besides colorectal cancer, SRSF6 expression is also associated with poor prognosis in T-cell acute lymphoblastic leukemia (T-ALL)." (PMID 34917618, 2021). "In colorectal cancer, SRSF6 was up‐regulated and associated with poor prognosis." (PMID 31729134, 2020). "Other splicing factors such as SRSF6 have been associated with colorectal cancer." (PMID 24553397, 2014). "Overexpression of LINC01133 inhibits invasion and migration in colorectal cancer by restricting the activity of SRSF6." (PMID 39941838, 2025). "Wan & al. recently determined the potential inhibitory effect on SRSF6 of indacaterol and its impact on cell migration in colorectal cancer cell model." (PMID 37904233, 2023). "LncRNA ZNF561-AS1 enhanced colorectal cancer survival and suppressed cell apoptosis through the miR-26a-3p/miR-128-5p/SRSF6 axis." (PMID 37240097, 2023). "Through a series of in vivo and in vitro experiments, SRSF6 has been found to promote the proliferation and metastasis of colorectal cancer cells." (PMID 35723346, 2022). "RNA sequencing results have demonstrated that SRSF6 regulates various alternative splicing events with various roles in colorectal cancer and the human pancreatic β-cell." (PMID 35454897, 2022). "Numerous studies have demonstrated the carcinogenic effects of SRSF6 in multiple cancers, including colorectal cancer, lung cancer, ovarian cancer, and T-cell ALL43." (PMID 35831551, 2022). "Consistent with this, upregulation of SRSF6 promotes proliferation of breast cancer cells, colorectal cancer cells, and lung cancer cells." (PMID 36409059, 2022). "SRSF6 is also highly expressed in skin cancer 70, pancreatic cancer 71, breast cancer 72 and colorectal cancer 73 and promotes the survival of cancer cells." (PMID 35711821, 2022). "As a member of the SR protein family, SRSF6 has been found to be upregulated in colorectal cancer samples." (PMID 35723346, 2022). "SRSF6 has been shown to be overexpressed in patients with colon and colorectal cancer, skin cancer, basal-cell carcinoma, and lung cancer, and its overexpression is associated with poor survival." (PMID 35454897, 2022). "Knockdown or using specific inhibitor of SRSF6 significantly inhibited colorectal cancer cell migration and invasion in vitro and metastasis in vivo." (PMID 34917618, 2021). "Knockdown or the use of specific inhibitor of SRSF6 significantly inhibited colorectal cancer cell proliferation." (PMID 34917618, 2021). "Another example is that lncRNA ZNF561-AS1 can sponge miR-26a-3p and miR-128-5p to upregulate SRSF6 expression in colorectal cancer." (PMID 34917618, 2021). "Mechanistically, LINC01133 acts as key downstream molecule in the TGF-β pathway and inhibits the EMT in colorectal cancer by directly binding to SRSF6 (serine and arginine rich splicing factor 6) as a target mimic." (PMID 29416704, 2018). "However, TGF-β can induce LINC01133 downregulation, and then allow SRSF6 to promote tumorigenesis in colorectal cancer." (PMID 34917618, 2021). "However, VEGF165b isoform expression actually decreased in colorectal cancer, which had SRSF6 overexpression." (PMID 34917618, 2021). "SRSF6 expression in colon and colorectal cancer has been studied extensively." (PMID 34917618, 2021). "Another natural drug namely indacaterol was shown to rescue SRSF6 associated aberrant splicing events, such as ZO-1 exon 23 skipping, and to reduce the viability of RKO, HCT116, and HCT8 colorectal cancer cells as well as to inhibit cancer growth in a colorectal cancer mouse model." (PMID 32596243, 2020).
colorectal cancer (continued). "More studies in larger cohorts may be required to evaluate SRSF6 expression in colorectal cancer." (PMID 34917618, 2021). "In colorectal cancer (CRC), SRSF6 was described to have an important role in alternative splicing mediating cancer progression." (PMID 37904233, 2023). "In colorectal cancer, lncRNA LINC01133 can block SRSF6 function in metastasis by interacting with SRSF6 protein." (PMID 34917618, 2021). "SRSF6 overexpression increased migration and invasion in breast cancer cells and induced epithelial–mesenchymal transition (EMT) in colorectal cancer cells." (PMID 34917618, 2021). "However, how SRSF6 regulates colorectal cancer cell EMT is still unknown." (PMID 29416704, 2018). "For instance, in colorectal cancer, LINC01133 directly binds to the splicing factor SRSF6." (PMID 39941838, 2025). "Among these hub genes, HNRNPL and HNRNPH1 genes may be molecular markers for early colorectal cancer diagnosis in MSS.TRA2A and SRSF6 may play important roles in PCRC metastasis." (PMID 39023715, 2024). "Furthermore, colorectal cancer also exhibits increased SRSF3, SRSF5, and SRSF6 expression." (PMID 36140826, 2022).
breast carcinoma (14 papers, 2013 to 2025). "Recent study also related SRSF6 expression level in peripheral blood mononuclear cells (PBMCs) as a potential biomarker of the presence of metastases in breast cancer patients." (PMID 37904233, 2023). "The implication of splicing factors SRSF4, SRSF6 and TRA2β was already demonstrated in cell proliferation and invasion promotion in normal mammary cells and in breast cancer cells." (PMID 37904233, 2023). "Using “the human protein atlas” database, survival curves related to SRSF6 RNA expression were calculated for breast cancer patients." (PMID 37904233, 2023). "circFBXL5 sponged miR‐660 to regulate SRSF6 expression and breast cancer proliferation and migration." (PMID 31729134, 2020). "However, when we took into account only patients with high grade breast cancer, a low expression of SRSF6 is related to a significant lower survival rate compared to high expression of SRSF6." (PMID 37904233, 2023). "Moreover, Park & al. demonstrated in MCF10 breast cancer cells overexpressing SRSF6 that ITGA5, ITGB2 and ITGB6 were overexpressed and alternative splicing variants of ITGB2, ITGB4, SRSF6 and ATXN2 were detected." (PMID 37904233, 2023). "circFBXL5 functions as a ceRNA to sponge miR-660 and upregulate SRSF6 expression in breast cancer." (PMID 34917618, 2021). "Estrogen indirectly inhibits SRSF6 expression in breast cancer cells." (PMID 34917618, 2021). "Our study highlighted the regulatory function of the circFBXL5/miR‐660/SRSF6 pathway in breast cancer progression, which could be potential therapeutic targets for breast cancer." (PMID 31729134, 2020). "Here, we found that SRSF6 was up‐regulated in breast cancer cell lines." (PMID 31729134, 2020). "Collectively, our study highlighted the regulatory function of the circFBXL5/miR‐660/SRSF6 pathway in breast cancer progression, which could be potential therapeutic targets for breast cancer." (PMID 31729134, 2020). "The circFBXL5/miR‐660/SRSF6 pathway played vital role in breast cancer progression and could be potential therapeutic targets for breast cancer." (PMID 31729134, 2020). "Moreover, SRSF6 was found to be upregulated in breast cancer cell lines and human tumors." (PMID 37904233, 2023). "However, SRSF6 overexpression decreased exon v6 inclusion in breast cancer cells." (PMID 34917618, 2021). "SRSF6 upregulation was related to promotion of cell proliferation and cell migration in MCF-10A breast cancer cells." (PMID 37904233, 2023). "Five out of the six splicing factors have been shown before to be overexpressed in breast cancer: HNRNPA1, HNRNPA2B1, HNRNPK, PTBP1 and SRSF6." (PMID 32756364, 2020). "The identified PBMC biomarkers (TMSB4X, HSPA4, S100A9, SRSF6, THBS1, CUL4A, and CANX) were significantly upregulated in the breast cancer patients at the metastatic stage compared to both the primary stage and healthy individuals (p < 0.001)." (PMID 32793473, 2020). "Youden index analysis also showed that five proteins including S100A9, SRSF6, THBS1, CUL4A, and CANX can accurately diagnose breast cancer patients at the metastatic and primary stages from healthy individuals." (PMID 32793473, 2020). "Finally, in silico analysis confirmed that a gene set consisting of S100A9, SRSF6, THBS1, CUL4A, and CANX were found to provide an insight for the identification of metastasis in breast cancer patients." (PMID 32793473, 2020). "We calculated the amount of each splicing factor and found that the HNRNPA2B1 level was slightly lower in breast cancer patients and all other splicing factor levels higher; this difference reached significance for PTBP1 (p < 0.05), HNRNPK_ex89 (p < 0.05) and SRSF6 (p < 0.01)." (PMID 32756364, 2020). "TMSB4X, SRSF6, and THBS1 displayed high connectivity degree values among the human protein–protein interaction networks according to the topological analysis, introducing these proteins as potential signatures in PBMCs of breast cancer patients." (PMID 32793473, 2020).
breast carcinoma (continued). "Additionally, among splicing regulators frequently altered in breast cancers (in >5% of tumors), we found different members of SR protein family (such as SRSF1, SRSF2, SRSF3, SRSF4, SRSF6, SRSF9, SRSF10, SRSF11) with at least one predicted binding motif in the CD44 v10 region." (PMID 33143085, 2020). "Finally, a gene set consisting of S100A9, SRSF6, THBS1, CUL4A, and CANX were introduced as potential candidate genes helpful in distinguishing metastatic from non-metastatic breast cancer patients." (PMID 32793473, 2020).
gastric cancer (10 papers, 2021 to 2025). A primary or metastatic malignant neoplasm involving the stomach. "For example, lncRNA CRNDE binds to SRSF6 protein and causes its ubiquitination and degradation by proteasome in gastric cancer cell." (PMID 34917618, 2021). "Multiple alternative splicing of SRSF6 also provides therapeutic targets for diseases such as rectal cancer, gastric cancer, and alcoholic liver disease." (PMID 39330852, 2024). "CRNDE restrains chemoresistance in gastric cancer through SRSF6-mediated alternative splicing of PICALM." (PMID 37194105, 2023). "In gastric cancer, SRSF6 is required for the resistance of gastric cancer cells to oxaliplatin and 5-FU." (PMID 34917618, 2021). "CRNDE could regulate the progression and chemoresistance of CRC via modulating the expression levels of miR-181a-5p and the activity of Wnt/β-catenin signaling, and CRNDE attenuates chemoresistance in gastric cancer via SRSF6-regulated alternative splicing of PICALM." (PMID 36911393, 2023). "In gastric cancer, autophagy induced by lncRNA CRNDE through the SRSF6/PICALM pathway during 5‐FU treatment promoted chemoresistance, similar to L‐OHP." (PMID 37837401, 2023). "Moreover, in vivo experimental studies recently showed that by modulating PICALM splicing through SRSF6, lncRNA CRNDE enhances the response of gastric cancer cells to chemotherapy." (PMID 37482612, 2023). "In principle, SRSF6 promotes phosphatidylinositol-binding clathrin assembly protein (PICALM) exon 14 inclusion to produce a full-length PICALM protein, which is required for the autophagy-induced resistance of gastric cancer cells to oxaliplatin and 5-FU." (PMID 34917618, 2021). "In gastric cancer (GC), lncRNA CRNDE directly binds to splicing protein SRSF6 to reduce its protein stability, which in turn reduces PICALM alternative splicing, triggering a significant switch from the short to long isoform to induce attenuated chemoresistance." (PMID 39937018, 2025).
colon cancer (8 papers, 2014 to 2025). "SRSF6 has been reported to be overexpressed in several cancers such as lung cancers and colon cancers." (PMID 40712780, 2025). "SRSF6 was reported to be significantly amplified in breast, lung, ovarian, and colon cancers, and promotes oncogenic splicing and further controls cell proliferation, metastasis, and drug resistance." (PMID 38723164, 2024). "In particular, the splicing factor SRSF6 is recognized as an oncoprotein that regulates the proliferation and survival of lung and colon cancer cells." (PMID 39023715, 2024). "SRSF6 silence also significantly inhibited colon cancer and lung cancer cell proliferation, colony formation in soft agar, and eventually repressed tumor formation." (PMID 34917618, 2021). "SRSF3 has also been proposed to be a proto-oncogene critical for cell proliferation and tumor induction and maintenance, whereas SRSF6 (SRp55) is amplified and is an oncoprotein in lung and colon cancers." (PMID 24842991, 2014). "Further in-depth studies of SRSF6 might provide new insights into the immune microenvironments of colon cancer, thereby developing new strategies of improving immunotherapy efficacy." (PMID 35454897, 2022).
pancreatic cancer (7 papers, 2021 to 2025). "In pancreatic cancer cells, miR-193a-5p is upregulated and involved in the activation of serine/arginine-rich splicing factor 6 (SRSF6), OGDHL, extracellular matrix protein 1 (ECM1), and epithelial-mesenchymal transition (EMT)." (PMID 40161373, 2025). "The inhibitor effectively suppressed the activity of SR proteins, SRSF4 and SRSF6, disrupting the RNA splicing process and inhibiting the growth and proliferation of the pancreatic cancer cells." (PMID 40126184, 2025). "Upregulation of miR-193a-5p (also a regulator of SRSF2 described previously) directly targets and inhibits SRSF6, and as a result, the splice variants of OGDHL and ECM1 conducive to tumorigenicity are expressed in pancreatic cancer." (PMID 34769047, 2021). "SRSF6 overexpression has been observed in lung and colon cancers and Huntington’s disease, but surprisingly, it is downregulated in pancreatic cancer." (PMID 34769047, 2021). "Moreover, SRSF6 reportedly increases the inclusion of OGDHL exon 3, thereby affecting pancreatic cancer cell metastasis." (PMID 36064747, 2022).
lung carcinoma (5 papers, 2021 to 2025). "Overexpression of several SR and SR-like proteins, in particular SRSF1, SRSF3, SRSF6 and TRA2β, was observed in lung cancer." (PMID 34065983, 2021). "SRSF6 gene is also reported to be amplified in some lung cancer patients (12%), and overexpressed." (PMID 34917618, 2021).